IL10 (interleukin 10)
Diseases named in the same sentence as IL10 in open-access papers (continued):
Sharing a sentence is not in itself a finding about the gene and the disease.
cutaneous leishmaniasis (51 papers, 2006 to 2025). Leishmaniasis affecting the skin. "The tissue repair process is critically important for rapid cure of cutaneous leishmaniasis, as demonstrated in L. (L. ) major murine cutaneous leishmaniasis, and is associated to reduced IL-10 and increased TNF-α, IFN-γ and the TGF-β pathway." (PMID 27579922, 2016). "Interleukin-10 overproduction has been associated with worse prognosis in human cutaneous leishmaniasis, while IFN-γ-dependent responses are associated with parasite killing and host protection." (PMID 26495321, 2015). "Interestingly, the L. (V.)panamensis LRV-1− reference strain (LpS94) showed elevated IL-10 production, reinforcing its association with a regulatory immune profile described in cutaneous leishmaniasis." (PMID 41471220, 2025). "Moreover, the frequency of IL-10 expression by γδT cells have been linked to an improvement of cardiac functions of cutaneous leishmaniasis patients, suggesting a potentially important role for γδT cells in the host responses." (PMID 36052077, 2022). "This increased susceptibility to cutaneous leishmaniasis could be due to the presence of serine proteases in whole-killed promastigotes of L. amazonensis, which promote an enhanced production of IL-10 and activate a Th2-type immune response." (PMID 32667458, 2020). "Moreover, skin lesions of patients affected by cutaneous leishmaniasis caused by L. (V.)braziliensis showed a stronger correlation between IL-10 expression and proinflammatory cytokines such as IFN-γ, IL-27, and IL-21, rather than with FoxP3+ cells." (PMID 29743809, 2018). "Moreover, a recent study has shown that IL-10-deficient BALB/c mice can control infection with L. major suggesting that IL-10 plays a key role in mediating the susceptibility and pathogenesis of cutaneous leishmaniasis." (PMID 23555077, 2013). "Adoptive transfer studies have shown that IL-10 produced by the CD4+ CD25− Foxp3− T cells suppressed the healing response in cutaneous leishmaniasis." (PMID 40502169, 2025). "In CD8+ T cells, the cytotoxic program induced by Blimp-1 appears to outweigh the antiinflammatory effect of IL-10 on cutaneous leishmaniasis." (PMID 38833303, 2024). "In cutaneous leishmaniasis patients, αβT cells and γδT cells secret inflammatory factors and IL-10, respectively to protect the hosts against the parasites invasion." (PMID 36052077, 2022). "IL-10 has several effects on cutaneous leishmaniasis, one of which is the capability to suppress NO production and leishmanicidal activity in macrophages, leading to the suppression of Th1 responses." (PMID 32867857, 2020). "It has been revealed that the IL-10 with immunosuppressive activity on the macrophages contributes to progression of disease in cutaneous leishmaniasis." (PMID 32133069, 2019). "On the other hand, IL-10 can down regulate IL-17 production in the immune cells separated from CL (Cutaneous leishmaniasis) and ML (mucocutaneous leishmaniasis) patients." (PMID 30811391, 2019). "As illustrated in cutaneous leishmaniasis (CL), plasmatic IL-10 levels are lower in patients with severe mucosal leishmaniasis (ML) compared to those with CL, suggesting the protective role of IL-10." (PMID 31870416, 2019). "Furthermore, BALB/c mice deficient in IL-10 could control the L. major infection, suggesting that this cytokine might play an important role in mediating susceptibility to and pathogenesis of experimental cutaneous leishmaniasis." (PMID 25933287, 2015). "The potential use of anti-IL-10 blocking mAb was tested in PBMC from individuals living in an endemic area of cutaneous leishmaniasis." (PMID 26495321, 2015). "Here, we explore, for the first time, the potential role of IL-10 blockade in humans infected with L. braziliensis and bring some perspectives on the generation of new immunotherapies for cutaneous leishmaniasis." (PMID 26495321, 2015). "Results suggest the potential immunotherapeutic use of partial IL-10 blockade in localized cutaneous leishmaniasis." (PMID 26495321, 2015).
cutaneous leishmaniasis (continued). "Apart from IL-10, IL-4 also induces Th2 responses and is particularly involved in the promotion of cutaneous leishmaniasis." (PMID 25368612, 2014). "Th2 cytokines, namely IL-4 regarding cutaneous leishmaniasis and IL-10 and TGF-β in the case of visceral disease, have been related with disease susceptibility and progression by induction of an M2 macrophage phenotype." (PMID 25368612, 2014). "Using this model we are the first to demonstrate that IL-10 can play a critical role in controlling pathology in cutaneous leishmaniasis." (PMID 23555256, 2013). "A particularly severe form of cutaneous leishmaniasis, termed mucosal leishmaniasis, exhibits decreased IL-10 levels and an exaggerated inflammatory response that perpetuates the disease." (PMID 23555256, 2013). "Specifically, in the model of cutaneous leishmaniasis, Tregs prevent complete eradication of the parasite from the host through IL-10 mediated mechanisms." (PMID 24205367, 2013). "A clear dichotomy between Th1-mediated protection (mediated by major cytokines IFNγ, IL-2, TNF) and Th2-mediated disease progression (mediated by major cytokines IL-10, IL-4) has been demonstrated in mice against cutaneous leishmaniasis." (PMID 21912560, 2012). "Although IL-10 secreting Th1 cells have been described recently in two murine models of toxoplasmosis, and cutaneous leishmaniasis, as far as we are aware, this is the first demonstration of IL-10 producing Th1 cells during human infections." (PMID 19343213, 2009). "Indeed, patients suffered with PKDL, cutaneous and muco-cutaneous Leishmaniasis exhibited a significant increase in IL-10 producing CD8 T cell population which directly corroborate with disease pathogenesis." (PMID 32203500, 2020). "In patients with localized cutaneous leishmaniasis a compromise is attained in which the parasite load is kept in check by an immune response whose magnitude is regulated by the action of regulatory cytokines such as IL-10 or TGF-β." (PMID 31637219, 2019). "LACK antigen from Leishmania braziliensis, Leishmania guyanensis, and Leishmania amazonensis induces the production of IFN-γ and IL-10 in peripheral blood mononuclear cells (PBMC) from patients with cutaneous leishmaniasis (CL), and IL-10 in those of naïve individuals." (PMID 29740446, 2018). "In this study, we showed that MoDCs are an important source of IL-10 in cutaneous leishmaniasis." (PMID 25309922, 2014). "Thus human IgG from both types of cutaneous leishmaniasis patients, when bound to amastigotes, can stimulate IL-10 production from human cells." (PMID 23675550, 2013). "In the group of patients with active cutaneous leishmaniasis the IFN-γ levels induced by stimulation with La were significantly higher and the levels of IL-10 significantly lower than those stimulated by LACK." (PMID 27600664, 2016). "In patients with cutaneous leishmaniasis derived from L. braziliensis infection, production of IFN-γ and IL-10 was detected in the skin lesions." (PMID 27350537, 2016). "In experimental cutaneous leishmaniasis in mice, natural T regulatory cells (CD4+CD25+FoxP3+) are a major source of IL-10, and these cells are crucial for maintenance of parasite persistence." (PMID 21912560, 2012). "IL-10 and TGF-β are present in lesions of L. major induced cutaneous leishmaniasis and contribute to the pathogenesis of long lasting disease forms." (PMID 23109946, 2012). "The aim of this study was to analyze the role of IL-10 and TGF-β in human cutaneous leishmaniasis due to Leishmania major infection." (PMID 23109946, 2012). "The levels of IL-5 and IL-10 production by PBMC were very low and similar in PBMCs from both disseminated leishmaniasis and cutaneous leishmaniasis patients." (PMID 16638143, 2006).
cutaneous leishmaniasis (continued). "Cutaneous leishmaniasis (CL) is believed to present an unbalanced Th1/Th2 response during its acute phase with clinical resolution being an IFN-γ-dependent event, whereas lesion progression and therapeutic failure are related to IL-10 overproduction." (PMID 26495321, 2015). "No studies have identified the cells making IL-10 within the lesions of cutaneous leishmaniasis patients, although within the peripheral blood monocytes and regulatory T cells were identified as IL-10 producers." (PMID 23555256, 2013). "Furthermore, the crucial role of IL-10 in Leishmania disease progression had been demonstrated, as has the detrimental role of neutrophils in the development of immunopathology during cutaneous leishmaniasis in the absence of IL-10." (PMID 33114674, 2020). "Taken together, the data obtained in this study suggest that CD4+ T lymphocytes and FoxP3+ T regulatory cells, as well as TGF-β+ and IL-10+ cells, although discrete, play an important role in the immunopathogenesis of nonulcerated or atypical cutaneous leishmaniasis." (PMID 29743809, 2018). "The addition of IL-27 to PBMC cultures from patients with CL and ML did not interfere with the production of IL-10 by these cells, confirming that IL-27 did not have an effect on regulating the strong inflammatory response observed in human cutaneous leishmaniasis in this study." (PMID 24485388, 2014). "In murine models, IFNγ- and IL-10-producing CD4+ T cells emerge during experimental infection with Toxoplasma gondii and in non-healing cutaneous leishmaniasis, where they were shown to protect mice against immune-related pathology at the cost of pathogen persistence." (PMID 41000872, 2025).
sarcopenia (51 papers, 2018 to 2026). Progressive decline in muscle mass due to aging which results in decreased functional capacity of muscles. "Higher levels of IL-6 and IL-10, both indicators of sarcopenia and muscle strength loss, underlay the ongoing inflammatory process compromising muscle quality in dependent patients." (PMID 38338718, 2024). "Increased IL-6 as well as IL-6/IL-10 serum levels were positively associated with degree of sarcopenia and increased with age—overall indicative of a systemic inflammatory status that cannot be compensated by anti-inflammatory IL-10 release." (PMID 39683624, 2024). "MCR was also significantly associated with low IL-10 and IL-10 to TNF-α ratio after adjusting for sarcopenia and body fat percentage." (PMID 37371414, 2023). "Blood was drawn, and inflammatory biomarkers associated with Sarcopenia (IL-2, IL-4, IL-5, IL-6, IL-8, IL-10, TNF, adiponectin, leptin, resistin, BDNF, sTNFr-1 and sTNFr-2) was analysed." (PMID 37365209, 2023). "Its reduced association with lamin A/C in IL10-KO muscle suggests Lmcd1 is also relevant to sarcopenia and fatigue in frailty and warrants further testing." (PMID 37936983, 2023). "Another study by Yu-Dong Rong investigating IL-6 and IL-10 in 82 elderly Chinese population with sarcopenia found that IL-6 level and IL-6/IL-10 ratio were positively associated with sarcopenia." (PMID 36309772, 2022). "Positive associations were present between the severity of sarcopenia and IL-6 and IL-17A levels, whereas there was an inverse correlation between the presence of sarcopenia and the IL-10 level." (PMID 35237317, 2022). "IL-10-deficient mice reduce skeletal muscle strength with age and become attractive models for sarcopenia." (PMID 35250869, 2022). "Either inflammatory cytokines, including TNF and IL-1β, or anti-inflammatory cytokines such as IL-10 have been implicated in sarcopenia-related frailty in humans and rodents." (PMID 33918334, 2021). "Fourthly, we included the most common inflammatory markers such as hs-CRP and IL-6, although many others (TNF-α, IL-10, etc.)that have been implicated in sarcopenia." (PMID 34911470, 2021). "Previous observational and review studies showed that sarcopenia is associated with elevated levels of inflammatory cytokine IL-6, IL-6/IL-10, and anti-inflammatory cytokine IL-10." (PMID 31906011, 2019). "Age, BMI, levels of physical activity, nutritional risk, VFA, IL-6, IL-10, IL-6/IL-10 ratio were independently associated with the presence of sarcopenia in univariate regression analyses." (PMID 30541467, 2018). "Secondly, the cross-sectional design limits us from identifying a cause-effect association between sarcopenia and IL-6 levels, IL-10 levels and IL-6/IL-10 ratios." (PMID 30541467, 2018). "Following adjustment for potential confounders (age, sex, BMI, physical activity, nutritional risk, VFA), positive associations were present between sarcopenia and IL-6 levels, IL-10 levels, and IL-6/IL-10 ratios." (PMID 30541467, 2018). "Sarcopenia was associated with increased levels of inflammatory cytokine IL-6, anti-inflammatory cytokine IL-10, and IL-6/IL-10 ratios." (PMID 30541467, 2018). "Age-related changes in body composition in sarcopenia, primarily more fat depositing in the abdomen and muscles, may be associated with serum IL-10 levels." (PMID 30541467, 2018). "To investigate this question, we measured serum concentrations of the inflammatory cytokine IL-6 and the anti-inflammatory cytokine IL-10, and estimated the association between IL-6 levels, IL-10 levels, and IL-6/IL-10 ratios with sarcopenia in elderly individuals." (PMID 30541467, 2018). "So far, few studies have examined whether the association exists between the antiinflammatory cytokine IL-10 and sarcopenia in elderly individuals." (PMID 30541467, 2018).
sarcopenia (continued). "However, although interleukin 10 is the only cytokine whose levels are statistically different between sarcopenic and not-sarcopenic individuals, its values do not correlate with any of the bacteria found to be associated with sarcopenia." (PMID 34357944, 2021). "Additionally, evidence exists to suggest age-associated inflammation and sarcopenia may be related to the change of IL-10 during aging." (PMID 30541467, 2018). "Numerous studies have found that pro-inflammatory factors such as IL-6, TNF-α, and C-reactive protein are significantly elevated in the serum of patients with sarcopenia, while the anti-inflammatory factor IL-10 is notably decreased." (PMID 40677895, 2025). "Previous studies have demonstrated potential causal correlation between IL-10, IP-10, M-CSF, Neutrophil-to-lymphocyte ratio (NLR) and sarcopenia-related traits." (PMID 41280389, 2025). "Lin also showed that people with COPD had significantly higher concentrations of the inflammatory factors IL-6 and IL-10, leading to increased degradation of muscle proteins and decreased muscle tissue, which exacerbated sarcopenia." (PMID 38635756, 2024). "The IC domains composite score was significantly associated with functional ability, perceived health, sarcopenia, and systemic inflammation biomarkers such GDF-15, IL-10, and IL-10/TNF-α ratio in pre-frail older adults." (PMID 38510450, 2024). "Several studies revealed that sarcopenia risk increases with circulating cytokines, such as CRP, IL-10, growth differentiation factor-15, and TNF-α." (PMID 39345889, 2024). "In a recent investigation, it was elucidated that moderate-intensity exercise significantly increased serum irisin levels and bolstered the presence of the anti-inflammatory factor interleukin-10 (IL-10) in elderly women with concurrent sarcopenia and OA." (PMID 38195597, 2024). "This study focused on randomized controlled trials (RCTs) that examined the effects of RT on interleukin-6 (IL-6), tumor necrosis factor-α (TNF-α), C-reactive protein (CRP), and interleukin-10 (IL-10) about sarcopenia." (PMID 38863698, 2024). "Serum IL-10 levels were reduced in patients with sarcopenia, and the sarcopenia severity correlated positively with IL-6 and TNF-α levels." (PMID 37962457, 2023). "Previous studies have shown that pro-inflammatory biomarkers, including IL-6, IL-10, IL-8, IL-15, CRP, TNF-α, and GDF-15, are associated with skeletal muscle decline and sarcopenia." (PMID 38026977, 2023). "MCR was significantly associated with IL-10, IL-10 to TNF-α ratio, sarcopenia, body fat indices and systemic inflammation." (PMID 37371414, 2023). "In contrast, combined exercise in people with sarcopenia increase thigh cross-sectional area and IL-10 and decreased TNF-α." (PMID 35250869, 2022). "Serum IL-10 level increases slightly in elderly sarcopenia, but it is considered to be a compensation for the chronic low-level inflammatory conditions." (PMID 35215448, 2022). "We found that the levels of inflammatory cytokines IL-6, IL-17A, and TNF-α were increased in sarcopenia patients, while the IL-10 level declined." (PMID 35237317, 2022). "More specifically, a variety of cytokines, including tumor necrosis factor (TNF)-α, interleukin (IL)-1, IL-2, IL-4, IL-6, IL-8, and IL-10 play a role in the development of sarcopenia." (PMID 36160136, 2022). "IL-10 knockout mice (IL-10−/−) have been used as a mouse model of sarcopenia, due to their reduced skeletal muscle mitochondrial function." (PMID 36499366, 2022). "There is evidence that levels of IL-6, IL-10, and the IL-6/IL-10 ratio increase in people with sarcopenia." (PMID 35250869, 2022). "Positive associations were present between the severity of sarcopenia and IL-6, IL-17A, and TNF-α levels, while there was an inverse correlation between the presence of sarcopenia and IL-10 level." (PMID 35237317, 2022).